RPS6KA1 (ribosomal protein S6 kinase A1)
Diseases named in the same sentence as RPS6KA1 in open-access papers:
RPS6KA1 is named in the same sentence as 105 diseases in open-access papers, as found by Europe PMC text mining. Sharing a sentence is not in itself a finding about the gene and the disease. The quoted sentences say what the papers report.
breast cancer (29 papers, 2008 to 2025). A primary or metastatic malignant neoplasm involving the breast. "In particular, homologs AKT1, AKT2, ERBB2, FGFR2, and PIK3CA in CGC play important roles in breast cancer progression, mediating breast cancer risk, corresponding to the driver candidates RPS6KA1, SGK1, PTK2, IGF1R, PIK3CB, and PRKDC predicted by DriverMP." (PMID 38091511, 2022). "The T allele of SNP rs2229714 which is located in the RPS6KA1 gene was also significantly associated with the increased risk of breast cancer." (PMID 32711446, 2020). "Mutations in RPS6KA1 could, therefore, modify the estradiol – breast cancer relationship." (PMID 29530003, 2018). "We found that genetic variants in RPS6KA1, ATF6B, CREB3L1 and SRC genes were associated with modified relationships between reproductive factors and breast cancer, especially the protective effect of the number of deliveries and the early age at menopause." (PMID 29530003, 2018).
lung cancer (15 papers, 2016 to 2025). A malignant neoplasm involving the lung. "Lastly, we showed that decreased expression of RPS6KA1, were associated with poor survival of lung cancer patients." (PMID 32928150, 2020). "We showed that the elevated expression level of RPS6KA1 was consistently associated with the increased overall survival of lung cancer patients with HR = 0.78, and a marginal significance of P = 0.09." (PMID 32928150, 2020). "Our results revealed that the elevated expression level of RPS6KA1 was associated with the increased overall survival of lung cancer patients, when comparing the high level of gene expression (>median) to low level (<=median) (Hazard Ratio [HR] = 0.64, P = 5.9 × 10− 3)." (PMID 32928150, 2020). "In a study conducted on human lung cancer samples, it was revealed that in metastatic lung cancer lesions, RPS6KA1 (RSK 1) was significantly reduced." (PMID 39436906, 2024). "RPS6KA1 has also been recognized as a therapeutic target in lung cancer and nodular type melanoma." (PMID 28388297, 2017). "In breast as well as in lung cancer, it was shown that high phosphorylation levels of EPHA2 induced by RPS6KA1 enhance cellular migration and tissue invasion capacity." (PMID 37414921, 2023).
colon carcinoma (8 papers, 2016 to 2026). "Research also has shown that genetic variation of RPS6KA1 is significantly associated with the risk of developing colon cancer." (PMID 33376727, 2020). "In vitro and in vivo experiments demonstrated that RPS6KA1 inhibits malignant progression of colon cancer and modulates fatty acid metabolism." (PMID 41751273, 2026).
prostate carcinoma (7 papers, 2018 to 2025). A carcinoma that arises from epithelial cells of the prostate gland. "Numerous protein kinases including AKT1, MAPK1/ERK, RPS6KA1/RSK1, cAMP-activated protein kinase (PKA), PAK1, PRKCI/nPKC-iota, PRKCE/nPKC-epsilon and PIM1 were reported to phosphorylate BAD in prostate cancer cells." (PMID 33668112, 2021).
acute myeloid leukemia (5 papers, 2021 to 2025). Acute myeloid leukemia (AML) is a group of neoplasms arising from precursor cells committed to the myeloid cell-line differentiation. "It has also been identified as a mediator of resistance to venetoclax/azacitidine, and the inhibition of RPS6KA1 may serve as a strategy to prevent or overcome resistance in the treatment of acute myeloid leukemia." (PMID 40678730, 2025). "Additionally, RPS6KA1 acts as an oncoprotein in acute myeloid leukemia, promoting disease progression." (PMID 40678730, 2025).
leukemia (4 papers, 2021 to 2024). A malignant (clonal) hematologic disorder, involving hematopoietic stem cells and characterized by the presence of primitive or atypical myeloid or lymphoid cells in the bone marrow and the blood. "Using an in vivo model of leukemia, RPS6KA1 has been shown to promote the self-renewal of hematopoietic stem cells and disease progression through the regulation of the mTOR pathway." (PMID 34502231, 2021).
Alzheimer disease (3 papers, 2017 to 2026). A progressive, neurodegenerative disease characterized by loss of function and death of nerve cells in several areas of the brain leading to loss of cognitive function such as memory and language. "For instance, it was found that LDW could simultaneously disturb the regulations of apoptosis and protein ubiquitination among biological processes, such as RPS6KA1, FHIT and AMFR, which may be the therapeutic targets of Alzheimer Disease." (PMID 29212201, 2017).
lung adenocarcinoma (3 papers, 2016 to 2020). A carcinoma that arises from the lung and is characterized by the presence of malignant glandular epithelial cells. "Our results showed three additional genes, CAPN8, HDGF and RPS6KA1, may be involved in smoking-related mutational signature, mediated by gene expression altered by tobacco smoking in lung adenocarcinoma." (PMID 32928150, 2020). "In lung adenocarcinoma, our results showed that smoking increased the expression of three genes, AHRR, GPR15, and HDGF, and decreased the expression of two genes, CAPN8, and RPS6KA1, which were consequently associated with increased smoking-related mutational signature." (PMID 32928150, 2020). "For lung adenocarcinoma, we found that the expression levels of three genes, GPR15, HDGF, and AHHR, were associated with increased smoking-related mutational signature, while an inverse association was observed for the other four genes, NWD1, KCNQ1, CAPN8 and RPS6KA1." (PMID 32928150, 2020). "However, we did not observe that these methylations were associated with tobacco smoking in lung adenocarcinoma, although consistent association directions were observed for HDG and RPS6KA1 (Data not shown)." (PMID 32928150, 2020).
Obesity (3 papers, 2015 to 2023). Accumulation of substantial excess body fat. "PCSK9, MST1, and RPS6K1 predominantly mediated the detrimental effect of sedentary behavior on CAD, while the effect of smoking was mainly mediated by RGMB, PCSK9, ITPKA, RPS6KA1, and AGER, which partially aligned with the observed association pattern between obesity and CAD." (PMID 38049831, 2023). "The detrimental effect of obesity on CAD appears to be primarily mediated by MAP1LC3A, ANGPTL4, RPS6KA1, PCSK9, ITPKA, and AGER." (PMID 38049831, 2023).
viral infection (2 papers, 2020 to 2021). "We confirmed variants with putative driver role of MAP10, MPZL1, RPS6KA1, SETD1B, TAOK2, TMEM127, and TNFRSF1A genes, and of genes linked to viral infections (DDX3X and RSF1) and DNA repair (PAXIP1)." (PMID 32321919, 2020).
Ewing sarcoma (1 paper, 2014). A small round cell tumor that lacks morphologic, immunohistochemical, and electron microscopic evidence of neuroectodermal differentiation. "One of these targets is ribosomal protein S6 kinase A1 (RSK1) which is directly downregulated by miR-125b in Ewing sarcoma cell lines, resulting in reduced cell growth and proliferation." (PMID 24774301, 2014).
gallbladder cancer (1 paper, 2014). "Serial analysis of gene expression showed that upregulation of ANXA2 activates RPS6KA1, a downstream component of the MAPK signaling pathway, thereby affecting the development and progression of gallbladder cancer." (PMID 25362534, 2014).
hepatocellular carcinoma (1 paper, 2025). A malignant tumor that arises from hepatocytes. "The RPS6KA1 gene encodes the ribosomal protein S6 kinase alpha-1, which positively regulates the activation of the AKT/NF-κB pathway in hepatocellular carcinoma tumorigenesis." (PMID 40678730, 2025).
rosacea (1 paper, 2020). A chronic erythematous skin disorder that affects the face. "Furthermore, in the GWAS catalog, the RPS6KA1 gene is associated with glucose homeostasis traits, sclerosis, and the symptom of rosacea." (PMID 31932636, 2020).
steatosis (1 paper, 2024). Increased lipid within the cytoplasm of cells. "Therefore, we selected the RPS6KA1 and LMCD1 genes as diagnostic for steatosis and AS, and the RPS6KA1 SYNP02, JAML and SERPINA3 genes as diagnostic for NASH and AS." (PMID 38606153, 2024). "To further discuss the potential role of the core genes RPS6KA1 and SERPINA3 in steatosis, NASH and AS, we analyzed pathways associated with a single gene using GSEA-KEGG." (PMID 38606153, 2024). "We found differential expression of RPS6KA1 in patients with steatosis and NASH, and of SERPINA3 only in those with NASH compared with normal individuals." (PMID 38606153, 2024). "We found that RPS6KA1 expression differed between the steatosis and NASH groups, with all AUCs being > 0.7, whereas LMCD1 expression differed only in the steatosis group." (PMID 38606153, 2024).
cancer (68 papers, 2000 to 2025). A tumor composed of atypical neoplastic, often pleomorphic cells that invade other tissues. "Progesterone Receptor (PGR) and Ribosomal protein S6 kinase (RPS6KA1) were identified as two core targets in the cancer risk prognostic model." (PMID 40678730, 2025). "GSEA enrichment analysis revealed that PGR and RPS6KA1 were upregulated in metabolic pathways related to matter and energy, while downregulated in developmental and cancer-related pathways." (PMID 40678730, 2025). "Through integrative analysis using univariate regression, LASSO-Cox regression, and multivariate Cox regression, PGR and RPS6KA1 were identified as core targets involved in curcumol’s anti-cancer effects in EC." (PMID 40678730, 2025). "The MAPK signaling pathway has been shown to be activated in many cancers that are resistant to drugs, and our study found that RPS6KA1, CACNA1B, and MAPK8IP3 were significantly enriched in the MAPK signaling pathway." (PMID 35168607, 2022). "For example, the signal transducers, RPS6KA1 and MAPK1, found in cluster F, also associate with other cancer tissue types." (PMID 28388297, 2017). "Of these, ERK2 (encoded by the gene MAPK1) was reported to increase the activity and phosphorylation of the oncoprotein RPS6KA1 (ribosomal protein S6 kinase, 90 kDa, polypeptide A1), leading to cancer cell proliferation." (PMID 28388297, 2017). "RPS6KA1’s role in promoting cell growth and survival may be compromised, potentially leading to reduced cancer cell proliferation." (PMID 39298437, 2024). "Moreover, SM significantly suppressed the leptin-associated phosphorylation of extracellular signal-regulated kinase 1/2 (ERK1/2) and ribosomal protein S6 kinase A1 (p90RSK), which are key kinases that ensure the survival and proliferation of cancer cells." (PMID 37895840, 2023). "Compared with paracancerous tissues, AKAP7, EFEMP1, EPN2 and LAMA2 were lowly expressed in cancer tissues, while RPS6KA1, SLC1A6, TRABD and ZNRD1 were highly expressed in cancer tissues." (PMID 37123010, 2023). "The identification of RPS6KA1 and WFS1 is interesting as previous studies have reported their role in the promotion of tumour progression and metastasis in various cancers." (PMID 32899298, 2020). "One way for sexual hormones to induce cancer is the ability of estradiol to stimulate BAD phosphorylation and prevent apoptosis, which is mediated via MEK/ERK/RPS6KA1 and PI3K and Akt pathways." (PMID 29530003, 2018). "RPS6KA1, WFS1, ANAPC4 and TUBB4A have not been investigated in EC prior to this, and further studies are indicated to elucidate how these genes may affect survival in cancer in general, as well as their role in EC." (PMID 32899298, 2020).
tumor (56 papers, 2000 to 2025). "The lower level of RPS6KA1 expression was statistically associated (p = 0.02) to larger tumor sizes." (PMID 27152840, 2016). "Furthermore, our validation results suggested that the loss of four mTOR-related genes (PTEN, FLCN, RRAGC, and RPS6KA1) was associated with enhanced long-term proliferation and target tumor cell killing." (PMID 35990699, 2022). "We can find that the expression of GNG7, MXRA7, ASB2, and PDGFD in tumor samples is significantly lower than that in normal samples, while the expression of RPS6KA1, CHMP4C, APOL1, and LYPD3 is reverse." (PMID 36225190, 2022). "Enrichment analysis of the global protein expression data across all tumor samples showed that the heme degradation pathway enzymes BLVRA and HMOX2, as well as the mitogenic kinase RPS6KA1, among others, are significantly upregulated in EGFRm samples." (PMID 35360705, 2022). "Nine genes were upregulated in tumor tissues, while the PRKCD, RPS6KA1, CAT, and VEGFC genes were downregulated." (PMID 36254009, 2022). "The results showed that RPS6KA1, PDGFD, APOL1, and LYPD3 are all upregulated in tumor tissues, which were consistent with GEPIA2." (PMID 36225190, 2022). "This crosstalk from MAPKs to β-catenin appears to be mediated through the phosphorylation of GSK3β and potentially by the ERK-mediated activation of the ribosomal proteins p70 S6 (officially known as RPS6KB2) and p90 RSK (officially known as RPS6KA1), as described in a variety of tumour cells." (PMID 24816560, 2014).
infection (11 papers, 2010 to 2025). The state of being infected such as from the introduction of a foreign agent such as serum, vaccine, antigenic substance or organism. "Notably, RPS6KA1—a serine/threonine kinase and key ERK1/2 substrate—exhibited sustained upregulation at 24 h, 48 h, and 72 h post-infection." (PMID 41305370, 2025).
RPS6KA1 also shares sentences with these, for which no sentence is quoted: melanoma (23 papers); ovarian carcinoma (7); atherosclerosis (6); glioma (6); cardiac hypertrophy (4); Coffin-Lowry syndrome (4); head and neck squamous cell carcinoma (4); ischemia (4); pancreatic cancer (4); Cerebral ischemia (3); cervical carcinoma (3); colorectal cancer (3); gastric cancer (3); glioblastoma (3); kidney disease (3); non-small cell lung carcinoma (3); cardiovascular disease (2); gastric adenocarcinoma (2); kidney damage (2); kidney stone (2); renal fibrosis (2); sarcoma (2); serous ovarian carcinoma (2); thyroid tumor (2); triple-negative breast carcinoma (2); adenoma (1); allergic rhinitis (1); astrocytomas (1); bladder cancer (1); breast tumors (1).
A further 57 diseases each share a sentence with RPS6KA1 in 1 paper.